RNU6-767P (RNA, U6 small nuclear 767, pseudogene)
Gene: Small nuclear RNA gene on chromosome 17 (17,170,083 to 17,170,189, forward strand). Ensembl gene ENSG00000206859.
Homologues: Orthologues: chimpanzee U6 (99% identical), macaque U6 (88% identical), mouse Gm24921 (87% identical), mouse Gm22583 (86% identical), guinea pig U6 (81% identical). Paralogues in human: RNU6-1309P (89% identical), RNU6-774P (89% identical), RNU6-1060P (88% identical), RNU6-1091P (88% identical), RNU6-116P (88% identical), RNU6-1175P (88% identical), RNU6-144P (88% identical), RNU6-19P (88% identical), RNU6-266P (88% identical), RNU6-434P (88% identical), RNU6-949P (88% identical), RNU6-1011P (87% identical), and 1282 more.